MALAT1 (metastasis associated lung adenocarcinoma transcript 1)
Diseases named in the same sentence as MALAT1 in open-access papers (continued):
Sharing a sentence is not in itself a finding about the gene and the disease.
Miscarriage (2 papers, 2019). A pregnancy that ends at a stage in which the fetus is incapable of surviving on its own, defined as the spontaneous loss of a fetus before the 22th week of pregnancy. "This case-control study was the first to evaluate the association between lncRNA MALAT1 polymorphisms and recurrent miscarriage susceptibility." (PMID 31024342, 2019). "In summary, our study confirmed the significant protective effect of the MALAT1 rs619586 G variant in recurrent miscarriage in a Chinese population." (PMID 31024342, 2019). "We further explored the associations between lncRNA MALAT1 gene polymorphisms (rs619586) and combined effects of protective genotypes and recurrent miscarriage susceptibility in analyses stratified by age and number of miscarriages." (PMID 31024342, 2019). "Future studies with larger sample sizes and inclusion of other factors that are important for miscarriage are needed to validate our findings regarding the roles of the lncRNA MALAT1 gene in recurrent miscarriage susceptibility." (PMID 31024342, 2019). "Genotype and allele frequencies of MALAT1 in recurrent miscarriage patients and controls." (PMID 31024342, 2019). "Our results suggested that the lncRNA MALAT1 rs619586 G allele was associated with a decreased risk of recurrent miscarriage, and the protective effect was most pronounced in women less than 35 years of age, and in the subgroup of women with two to three prior miscarriages." (PMID 31024342, 2019). "However, future studies with larger sample sizes and practical experiments should be performed to further validate the roles of MALAT1 gene variants in recurrent miscarriage susceptibility." (PMID 31024342, 2019). "The rs619586 G variant may reduce the risk of miscarriage by regulating the expression of MALAT1." (PMID 31024342, 2019). "Similarly, in our case-control study, the results suggested that the MALAT1 gene rs619586 G variant decreased the risk of recurrent miscarriage in a southern Chinese population and that it was likewise a protective factor against recurrent miscarriage susceptibility." (PMID 31024342, 2019). "Studies have also confirmed that the expression level of MALAT1 was reduced in the villus samples of recurrent miscarriage patients and the regulation of MALAT1 is one of the factors that contributes to the pathogenesis of recurrent miscarriage." (PMID 31024342, 2019). "Therefore, further studies of the functional role of MALAT1 in miscarriage are needed." (PMID 31024342, 2019). "Although we did not detect the expression of MALAT1 in miscarriage patients, we speculate that the rs619586 G variant may reduce the risk of miscarriage by regulating the expression of MALAT1." (PMID 31024342, 2019). "However, reports have not focused on whether the MALAT1 gene polymorphism is associated with miscarriage susceptibility." (PMID 31024342, 2019). "Currently, the molecular mechanism of MALAT1 in miscarriage patients is still not clear." (PMID 31024342, 2019).
mycosis fungoides (2 papers, 2021 to 2022). Classical mycosis fungoides is the most common type of mycosis fungoides (MF), a form of cutaneous T-cell lymphoma, and is characterized by slow progression from patches to more infiltrated plaques and eventually to tumors. "Long non-coding RNA metastasis-associated lung adenocarcinoma transcript 1 (MALAT1) was especially increased in mycosis fungoides tissue." (PMID 35203305, 2022).
non-alcoholic steatohepatitis (2 papers, 2021 to 2023). "MALAT1 may mediate chemokines by regulating C-X-C motif chemokine ligand 5 (CXCL5) in hepatic stellate cells in the occurrence of non-alcoholic steatohepatitis (NASH) and fibrosis in patients with NAFLD." (PMID 35145971, 2021).
non-Hodgkin lymphoma (2 papers, 2016 to 2023). Distinct from Hodgkin lymphoma both morphologically and biologically, non-Hodgkin lymphoma (NHL) is characterized by the absence of Reed-Sternberg cells, can occur at any age, and usually presents as a localized or generalized lymphadenopathy associated with fever and weight loss. "Our study investigated MCL, an aggressive type of non Hodgkins lymphoma, and found that the expression of MALAT1 was significantly higher in MCL compared to normal B-cells (P < 0.01)." (PMID 27998273, 2016).
normal-tension glaucoma (2 papers, 2022 to 2023). "For down-regulated DEmiRNAs, miR-1 and its target gene MALAT1 are associated with lower risk and severity of normal-tension glaucoma (NTG)." (PMID 37940950, 2023). "For instance, the lncRNA metastasis associated lung adenocarcinoma transcript 1 (MALAT1) has been shown to act as a ceRNA and regulates the IL-6 expression by sponging miR-1, thus affecting the severity of normal-tension glaucoma." (PMID 35800083, 2022).
obstructive sleep apnea (2 papers, 2021 to 2025). "MALAT1 and nucleotide binding and oligomerization domain-like receptor family pyrin domain (NLRP3) are overexpressed in the brain tissue of T2DM patients with obstructive sleep apnea (OSA), while miR-224-5p is downregulated." (PMID 34712322, 2021).
osteonecrosis (2 papers, 2021 to 2022). A none disease characterized by death of bone tissue due to a lack of blood supply. "We examined the potential mechanisms of action of the long non‐coding RNA MALAT1, microRNA 329‐5p and mRNA in glucocorticoid‐induced osteonecrosis of the femoral head." (PMID 33939272, 2021). "In conclusion, MALAT1 played a vital role in the pathogenesis of glucocorticoid‐induced osteonecrosis of the femoral head by sponging miR‐329‐5p to up‐regulate PRIP." (PMID 33939272, 2021). "Knockdown of MALAT1 decreased PRIP expression in rats and cultured cells and rescued glucocorticoid‐induced osteonecrosis of femoral head in rats." (PMID 33939272, 2021).
pancreatic adenocarcinoma (2 papers, 2013 to 2024). "We tested whether MALAT1 expression and NR4A1-downstream RE accessibility were strongly correlated in cancer types, such as BRCA, versus low- or no-correlation cancers, such as pancreatic adenocarcinoma (PDAC)." (PMID 38791553, 2024).
polyp (2 papers, 2019 to 2023). A usually exophytic mass attached to the underlying tissue by a broad base or a thin stalk. "In addition to a role in restricting polyp formation, MALAT1 also contributes to abnormal intestinal polyp growth at a later stage." (PMID 37325561, 2023). "Comparison of the MALAT1 promoter methylation pattern between polyp types and tumor tissue groups was not significant either (p=0.437)." (PMID 32099603, 2019). "In addition, no significant hypermethylation of MALAT1 was observed between the other patients’ clinicopathological data in both polyp 46/66 and tumor tissues 20/66." (PMID 32099603, 2019).
prion disease (2 papers, 2023). A transmissible disease that is caused by a protein that is able to induce abnormal folding of normal cellular proteins, leading to characteristic spongiform brain changes, which are associated with neuronal loss without an inflammatory response. "Because this tool compound is less potent than the Malat1 ASO, we used a 500 μg dose, which modifies prion disease in mice and lowers whole hemisphere PrP to an estimated 56% residual after 4 weeks." (PMID 37188501, 2023).
proliferative vitreoretinopathy (2 papers, 2016 to 2024). Vitreoretinal membrane shrinkage or contraction secondary to the proliferation of primarily retinal pigment epithelial cells and glial cells, particularly fibrous astrocytes, followed by membrane formation. "Increased MALAT1 expression has also been observed in blood and fibrovascular membranes in another eye disease, proliferative vitreoretinopathy." (PMID 38674413, 2024). "MALAT1 expression was also detected in primary RPE cells incubated with proliferative vitreoretinopathy (PVR) vitreous samples." (PMID 27019196, 2016).
prostate tumor (2 papers, 2019 to 2023). "MALAT1 is upregulated in prostate tumor tissue and cell line of human beings." (PMID 31572428, 2019).
testicular cancer (2 papers, 2019 to 2023). A primary or metastatic malignant neoplasm that affects the testis. "In terms of mechanisms, LncRNA MALAT1 contributed to testicular cancer progression through the upregulation of IGF2BP2 by binding to miR-204." (PMID 37365581, 2023).
thoracic aortic aneurysm (2 papers, 2020 to 2022). An aneurysm formed in the wall of the proximal portion of the descending aorta proceeding from the arch of the aorta. "The lncRNA MALAT1 (metastasis-associated lung adenocarcinoma transcript 1) can form a complex with HDAC9 and the chromatin remodeling enzyme BRG1, which results in the dysfunction of smooth muscle tissue and contributes to thoracic aortic aneurysms." (PMID 33291485, 2020). "In contrast, BRG1 was demonstrated to be upregulated in the thoracic aortic aneurysm (TAA), and BRG1, in cooperation with long, noncoding RNAs MALAT1 and HIF1 α-antisense RNA1, was shown to mediate the epigenetic regulation of VSMC dysfunction and apoptosis in TAA." (PMID 36066968, 2022).
thymoma (2 papers, 2022). A neoplasm arising from the epithelial cells of the thymus. "In thymoma and thymic carcinoma, MALAT1 regulates cell proliferation by acting as an miR-145-5p sponge and contributing to c-MYC induction, following its change in subnuclear localization due to METTL3 methylation." (PMID 35529877, 2022).
thyroid tumor (2 papers, 2021 to 2022). A benign or malignant neoplasm affecting the thyroid gland. "We aimed to evaluate the common mutated genes (JMJD1C, MALAT1, MUC16, PDZD2, PKHD1, RYR1, SLA and TTN) between thyroid tumor and normal samples." (PMID 35996174, 2022). "MALAT1 is also expressed in normal thyroid (NT) and thyroid tumors, with increased expression during progression from NT to papillary thyroid carcinomas (PTC)." (PMID 34069428, 2021). "Knockdown of MALAT1 inhibited cell proliferation and invasion of human thyroid tumor cell lines." (PMID 34069428, 2021).
Ureteral obstruction (2 papers, 2023 to 2025). Obstruction of the flow of urine through the ureter. "Using a murine EC lineage-tracing model, we observed expression of the conserved lncRNA metastasis-associated lung adenocarcinoma transcript 1 (Malat1) to be elevated in ECs upon kidney injury; either by ischemia-reperfusion injury or by unilateral ureteral obstruction (UUO)." (PMID 40978530, 2025). "Here, the aim of our study was to investigate the dysregulate expression of lncRNA MALAT1 in TGF-β1 treated HK2/NRK-49F cells and unilateral ureteral obstruction (UUO) mice model, defining its effects on HK2/NRK-49F cells and UUO mice fibrosis process through the miR-124-3p/ITGB1 signaling axis." (PMID 37872392, 2023).
uterine corpus endometrial carcinoma (2 papers, 2019 to 2021). A endometrial carcinoma (disease) that involves the body of uterus. "Additionally, MALAT1 also has been supported to be related to uterine corpus endometrial carcinoma and connected 7 modules in UCEC dataset." (PMID 30732558, 2019).
airway hyperresponsiveness (1 paper, 2022). "The most prominent readout to detect this protective effect of Malat1 deficiency on airway hyperresponsiveness was hysteresivity (η)." (PMID 36105289, 2022).
alcoholic liver diseases (1 paper, 2025). A disorder caused by damage to the liver parenchyma due to alcohol consumption. "Specifically, MALAT1 expression was examined in 7 HBV-HCC datasets, 7 HCV-HCC datasets, 4 NAFLD-related HCC datasets, and 2 datasets from patients with alcoholic liver disease (ALD)." (PMID 40860202, 2025).
allergic asthma (1 paper, 2020). A asthma with a basis in a pathological type I hypersensitivity reaction. "In their work, Liang and Tang propose that the lncRNA metastasis-associated lung adenocarcinoma transcript 1 (MALAT1) is a key determinant that promotes the Th2 phenotype in allergic asthma." (PMID 32292999, 2020). "Thus, this work establishes MALAT1 as a key orchestrator of Th2 skewing in allergic asthma." (PMID 32292999, 2020).
amyotrophic lateral sclerosis (1 paper, 2022). Amyotrophic lateral sclerosis (ALS) is a neurodegenerative disease characterized by progressive muscular paralysis reflecting degeneration of motor neurons in the primary motor cortex, corticospinal tracts, brainstem and spinal cord. "Interestingly, both MALAT1 and NEAT1 are also deregulated in amyotrophic lateral sclerosis (ALS), which is a fatal neurodegenerative disorder characterized by progressive degeneration of motor neurons in the spinal cord, brainstem, and motor cortex." (PMID 35796900, 2022).
anemia (1 paper, 2025). A reduction in the number of red blood cells, the amount of hemoglobin, and/or the volume of packed red blood cells. "A low MALAT1 expression (OR = 9.33; p = 0.006) and RT (OR = 16.71; p = 0.006) were associated with a higher probability of anemia." (PMID 40150019, 2025). "In patients with post-RT anemia (hemoglobin < 12 g/dL), both low MALAT1 (median: 0.31 vs. 0.44; p = 0.023) and NEAT1 expression (median: 0.30 vs. 0.43; p = 0.008) were observed compared to those with normal hemoglobin levels." (PMID 40150019, 2025).
Angelman syndrome (1 paper, 2018). A neurogenetic disorder characterized by severe intellectual deficit and distinct facial dysmorphic features. "Even the non-coding genome is little understood but present in survival associated mitochondrial melanoma specific oncogenic non-coding RNA (SAMMSON), Angelman’s syndrome (alteration of the UBE3A gene expression), and metastasis-associated lung adenocarcinoma transcript 1 (MALAT1)." (PMID 30551598, 2018).
Anterior polar cataract (1 paper, 2019). "Next, we provided further evidence of MALAT1 being significantly upregulated in human PCO-attached LECs and in LECs obtained from patients with anterior polar cataracts." (PMID 31143769, 2019). "In addition, upregulation of MALAT1 and downregulation of miR-26a were detected in human posterior capsule opacification (PCO) attached LECs and the LECs obtained from patients with anterior polar cataracts by quantitative RT-PCR (qRT-PCR)." (PMID 31143769, 2019).
Arthritis (1 paper, 2025). Inflammation of a joint. "Further in vivo animal studies showed that inhibition of MALAT1 greatly promoted the differentiation of SMSCS into chondrocytes and delayed the progression of arthritis." (PMID 40635749, 2025).
autoimmune myocarditis (1 paper, 2018). Autoimmune myocarditis is an autoimmune disease that affects the heart. "The adoptive transfer of MALAT1-overexpressing DCs promoted cardiac allograft survival and protected from the development of experimental autoimmune myocarditis, accompanied with increasing antigen-specific regulatory T cells." (PMID 30150986, 2018). "Finally, we successfully validated the therapeutic effect of MALAT1 on cardiac graft rejection and autoimmune myocarditis by the transfer of MALAT1-overexpressing DCs." (PMID 30150986, 2018).
Autoimmunity (1 paper, 2025). The occurrence of an immune reaction against the organism's own cells or tissues. "Another lncRNA, MALAT1, is broadly expressed in immune cells and has garnered attention for orchestrating epigenetic and transcriptional mechanisms in autoimmunity." (PMID 41376628, 2025).
Azoospermia (1 paper, 2024). Absence of any measurable level of sperm,whereby spermatozoa cannot be observed even after centrifugation of the semen pellet. "We analyzed MALAT1 levels in two gene expression profiling datasets comprising patients with obstructive azoospermia (OA) who have normal spermatogenesis and 13 patients with iNOA." (PMID 39681821, 2024).
bacterial pneumonia (1 paper, 2024). Acute infection of the lung parenchyma caused by bacteria (e.g., Streptococcus pneumoniae, Haemophilus influenzae, Chlamydia pneumoniae, Mycoplasma pneumoniae, and Legionella pneumophila). "Bacterial pneumonia causes more inflammation in the arteries than viral pneumonia does, which might be the reason why the MALAT1 expressions are significantly higher in patients with bacterial pneumonia than those with viral pneumonia." (PMID 39061025, 2024).
Behçet’s disease (1 paper, 2025). "The current study was deployed to evaluate the role of metastasis-associated lung adenocarcinoma transcript 1 (MALAT1) and miR-155, along with the inflammatory markers, TNFα and IL-6, and the adhesion molecule, cluster of differentiation 106 (CD106), in Behçet’s disease (BD) pathogenesis." (PMID 39798064, 2025).
benign breast diseases (1 paper, 2022). "In the current study, MALAT1 was down-regulated but SNCG and HOTAIR were significantly up-regulated in patients with benign breast diseases." (PMID 36376369, 2022).
benign pancreatic tumours (1 paper, 2016). "And H19, HOTAIR, HOTTIP, MALAT1, and PVT1 levels did not significantly differ between NPT and benign pancreatic tumours (BPT) tissues (p values were 0.522, 0.759, 0.200, 0.631, and 1.000, respectively)." (PMID 27028998, 2016).
blinding (1 paper, 2025). "Thus, regulating MALAT1 could help protect mitochondria and provide a possible new target to inhibit/prevent the development of blinding disease in diabetic patients." (PMID 40650203, 2025).
bone marrow fibrosis (1 paper, 2021). "Among these, high levels of LINC01268, MALAT1 or GAS5 correlate with detrimental clinical variables, such as high count of leukocytes and CD34+ cells, severe grade of bone marrow fibrosis and presence of splenomegaly." (PMID 34638230, 2021). "Accordingly, MALAT1 (p = 0.0004) and GAS5 (p = 0.0023) levels positively correlate with a more severe grade of bone marrow fibrosis." (PMID 34638230, 2021). "In particular, high levels of LINC01268, GAS5 and MALAT1, correlated with detrimental features of MF, such as high WBC count, increased number of circulating CD34+ cells, marked LDH activity, presence of splenomegaly and a more severe grade of bone marrow fibrosis." (PMID 34638230, 2021).
breast adenocarcinoma (1 paper, 2024). "For example, the overexpression of the lncRNAs metastasis-associated lung adenocarcinoma transcript 1 (Malat1) and Hox transcript antisense RNA (HOTAIR) has been strongly associated with metastatic lung and breast adenocarcinomas." (PMID 39195572, 2024).
cerebral amyloid angiopathy (1 paper, 2023). "The top differentially expressed genes (DEGs) in db/db mouse endothelial cells included Malat (encoding metastasis-associated lung adenocarcinoma transcript 1), which may be involved in angiogenesis, and Cts3, which is dysregulated in cerebral amyloid angiopathy." (PMID 37351595, 2023).
cervical dysplasia (1 paper, 2023).
childhood leukemia (1 paper, 2023). An acute or chronic leukemia that occurs during childhood. "Moreover, NEAT1 has been previously implicated with chemoresistance in cancer, and both NEAT1 and MALAT1 have been associated with poor prognosis in childhood leukemia." (PMID 37528411, 2023).
choroidal neovascularization (1 paper, 2025). An eye disorder described by the growth of new blood vessels that originate from the choroid through a break in the Bruch membrane into the sub–retinal pigment epithelium (sub-RPE) or subretinal space. "This study determined the role of circRNA MALAT1 (circ-MALAT1) in Choroidal Neovascularization (CNV)." (PMID 40997603, 2025).
chronic heart failure (1 paper, 2025). "Metastasis-Associated Lung Adenocarcinoma Transcript 1 (MALAT1) was found to be downregulated in a rat model of chronic heart failure subjected to 6 weeks of aerobic treadmill training (5 days/week), accompanied by improved cardiac function and suppression of the PI3K/Akt pathway." (PMID 40822014, 2025). "In a chronic heart failure model using adult male Sprague-Dawley rats, six weeks of aerobic treadmill training (5 days/week) improved cardiac function by downregulating the lncRNA MALAT1 and upregulating miR-150-5p, thereby modulating the PI3K/Akt signaling pathway." (PMID 40822014, 2025).